CRP (C-reactive protein)
Diseases named in the same sentence as CRP in open-access papers (continued):
Sharing a sentence is not in itself a finding about the gene and the disease.
anemia (continued). "On univariate analysis, performance status; anemia; hypoalbuminemia; preoperative levels of BChE, corrected calcium, and C-reactive protein; and distant metastasis status were significantly associated with OS." (PMID 24741368, 2014). "In the present case, making an accurate diagnosis was complicated by a high CA-125 level associated with anemia and high levels of inflammatory markers (CRP and fibrinogen)." (PMID 24962423, 2014). "Baseline serum selenium deficiency pre-ART was associated with country of origin, anemia, CRP concentrations, and previous TB." (PMID 25401501, 2014). "Anemia is associated with ovarian malignancy, which is also commonly associated with high levels of fibrinogen and CRP." (PMID 24962423, 2014). "Anemia (OR: 1.89, 95% CI: 3.11–1.14), lower concentrations of albumin (OR: 4.46, 95% CI: 2.52–7.86), and higher levels of log10 CRP (OR: 1.79, 95% CI: 1.20–2.65) were also associated with greater serum selenium deficiency." (PMID 25401501, 2014). "In 50% of cases there are elevated serum levels of CRP and increased erythrocyte sedimentation rate, rarely in association with fever and anemia, features which can regress after HCA resection." (PMID 23691331, 2013). "The baseline CRP levels were significantly associated with anemia (P = 0.003, r = 0.278), LDH (P < 0.0001, r = 0.379), and plasma EBVDNA copy level (P = 0.0001, r = 0.352)." (PMID 24130817, 2013). "In female patients with hypergammaglobulinemia, the presence of leukopenia, anemia, and normal CRP was 95% predictive of underlying autoimmune disease." (PMID 24180594, 2013). "Of those with Iron deficiency anaemia 3 (5.8%) had raised CRP levels compared to 2 (7.7%) of those with anaemia of chronic disease." (PMID 24194926, 2013). "Multivariate analysis showed that male gender, age, tachycardia, anemia, thrombocytopenia, and CRP>5 mg/l were independently associated with malaria." (PMID 24069477, 2013). "In matched multivariate analysis, male gender, age>15 years, tachycardia, anemia, thrombocytopenia and CRP>5 mg/l remained independently associated with malaria as compared to DF." (PMID 24069477, 2013). "We aimed to test the association between serum CRP and serum ferritin and its impact on the severity of anemia of regular HD patients, and to determine their association with malnutrition-inflammation complex syndrome." (PMID 25340139, 2013). "The association between MD and thrombocytopaenia, anaemia, masculine gender, elevated CRP level, frequent transfusions persisted in bivariate analysis but not in multivariate analysis probably due to the loss of power." (PMID 22549018, 2012). "In 31 (34%) of all patients with anemia, values of iron, ferritin, and transferrin saturation had been measured; in another 32 patients, an iron-deficiency anemia was diagnosed due to microcytosis and CRP levels." (PMID 22899905, 2012). "Among children under 2 years of age, 17% of all cases of anemia were attributable to ID along with deficiencies in vitamin B12 and folate and high plasma CRP (approximately 3% for each risk factor)." (PMID 22574149, 2012). "Anaemia, severe thrombocytopaenia, male gender, high CRP level and LDC diagnosis were significantly associated with co-infection in multivariate analysis." (PMID 22549018, 2012). "In view of the iron status of the two groups, it would be reasonable to assume that the group with normal C-reactive protein had true iron deficiency anaemia, while the anaemia of the high C-reactive protein group was predominantly that of chronic disease." (PMID 21547258, 2011). "After controlling other significant variables and CRP status, anemia and ZD were associated with OR of 2.37 (95% CI: 1.96-3.33)." (PMID 22126192, 2011). "CRP has been associated with complement mediated haemolysis of infected erythrocytes and subsequent anaemia, but CRP has also been implicated in the defence against pre-erythrocytic stages of malaria." (PMID 19545442, 2009).
anemia (continued). "The constitutional symptoms, such as fever, weight loss, anemia, arthralgias and rash, rely on an immunologic response with an increase of CRP, IL-6 and γ-globulin due to bleeding and degeneration within the mass and releasing tumor fragments." (PMID 19818150, 2009). "Biochemical analysis revealed significantly lower serum iron, ferritin, transferrin saturation, albumin, and prealbumin levels among anemic girls, alongside elevated total iron-binding capacity and CRP, indicating a predominance of iron deficiency anemia with an inflammatory component." (PMID 42232018, 2026). "A CARD diagnosis was also associated with higher inflammatory status (raised CRP), anaemia and iron deficiency and in those off systemic anticancer therapy, which may be reflective of more advanced disease." (PMID 41043860, 2025). "Among the WRA, the observed prevalence was significantly greater than the prevalence expected by chance alone for anemia co-occurring with ID by SF (19% vs 14%; P = 0.002), any ID (23% vs 17%; P = 0.001), vitamin A deficiency (1% vs 0.3%; P = 0.028), and elevated CRP (5% vs. 3%; P = 0.023)." (PMID 40526587, 2025). "Investigations revealed iron-deficiency anemia and elevated C-reactive protein." (PMID 40979022, 2025). "Additionally, the significantly higher CRP levels observed in anemic patients before discharge indicate the persistence of chronic inflammation, which can be linked to the systemic effects of anemia in COPD patients." (PMID 40282996, 2025). "Serological abnormalities associated with IVLBCL may include elevated levels of CRP, thrombocytopenia, anemia, hypoproteinemia, as well as increased Cr and bilirubin levels." (PMID 39949737, 2025). "Thus, the combination of normocytic anemia and elevated CRP levels across both groups points toward a complex interplay of inflammation and nutritional risk in contributing to anemia in geriatric patients." (PMID 40836330, 2025). "Among the 4557 anemic children, 3635 children had valid hemoglobin, serum ferritin, CRP, erythrocyte folate, and vitamin B12 values, of which 2639 (72.6%, 95% CI: 68·7–76·1) had anemia with micronutrient deficiencies (at least one of iron, vitamin B12, folate)." (PMID 38236794, 2024). "Some studies suggest that high CRP levels in children with iron deficiency anemia may be an indicator of inflammatory processes." (PMID 39797144, 2024). "While multiple potential etiologies exist for elevated CRP, a recent study in patients with anemia of CKD on HD indicated there may be a causal relationship between elevated CRP levels and ESA hyporesponsiveness." (PMID 39597872, 2024). "Anaemia was significantly associated with impaired liver function, portal hypertension, more advanced Barcelona Clinic Liver Cancer stage and elevated C-reactive protein (CRP)." (PMID 38848660, 2024). "Through adjustment for various potential confounders, including age, gender, anemia, and leukocyte count, multivariate binary regression analysis was performed to further validate the status of CRP as an autonomous risk factor for sarcopenia (OR: 1.151, 95% CI: 1.070−1.238, and P < 0.001)." (PMID 39502753, 2024). "Older age, history of tuberculosis, presence of cavity, consolidative radiologic features, AFB smear positivity, anemia, and high C-reactive protein were common significant factors associated with the all-cause mortality and clinical or radiographic progressive disease of NTM-LD." (PMID 37147519, 2023). "Some serum biomarkers, including anemia, lymphopenia, thrombocytopenia, elevated levels of CRP, lactate dehydrogenase, and D-dimer, may be associated with mortality." (PMID 38127882, 2023). "Pure iron deficiency anemia is defined in the case of ferritin serum levels < 30 μg/L and the normal value of CRP; chronic disease anemia is defined by ferritin serum level > 100 μg/L and high levels of CRP." (PMID 37686856, 2023).
anemia (continued). "In conclusion, older age, history of TB, presence of cavity, consolidative radiologic features, AFB smear positivity, anemia, and high CRP were common significant factors associated with the all-cause mortality and clinical or radiographic progressive disease of NTM-LD." (PMID 37147519, 2023). "A similar study showed that an increase in CRP of 1 mg/L may increase the risk of anaemia by 80–90%." (PMID 37048531, 2023). "Older age, history of tuberculosis, presence of cavity, consolidative radiologic feature, AFB smear positivity, anemia, and high CRP were common significant factors associated with the all-cause mortality and clinical or radiographic progressive disease of NTM-LD." (PMID 37147519, 2023). "Additionally, in rheumatic patients, high levels of interleukin-1β were associated with anaemia, neutrophilia, lymphopenia, low albumin levels, and increased CRP, which are elements partly used in several of the inflammation-scores." (PMID 35027001, 2022). "Iron deficiency is very common in IBD patients due to inadequate dietary intake, malabsorption and chronic blood loss and has been associated with disease activity, while increased CRP levels have been linked with increased prevalence of anemia in patients with IBD." (PMID 36570124, 2022). "The current state of the art indicates that comparing hepcidin to CRP may be a quick and simple way to determine whether anaemia is the result of an iron deficiency, an inflammation, or a mixture of both." (PMID 36612220, 2022). "Moreover, Se levels were also associated with the incidence of new-onset heart failure, anemia, iron deficiency, high C-reactive protein (CRP) levels, and current smoking." (PMID 35847596, 2022). "Furthermore, preoperative anemia and elevated serum levels of bilirubin and CRP were associated with postoperative complications." (PMID 34086792, 2021). "Moreover, low eGFR, high CRP and a combination of two and above determinants were associated with the development of anaemia during follow-up." (PMID 34372781, 2021). "In 2005, for the first time, we reported that, in a population of advanced ovarian cancer assessed at diagnosis prior to any antineoplastic treatment, the severity of cancer-related anemia was associated with a status of chronic inflammation characterized by high levels of IL-6, CRP, and fibrinogen." (PMID 33550983, 2021). "Low eGFR and high CRP were associated with the presence of anaemia." (PMID 34372781, 2021). "In addition, compared to participants with 0 or 1 determinant, the pooled adjusted OR for a combination of ≥2 of the three significant determinants (iron deficiency, low eGFR and high CRP) on the presence of anaemia was 4.53 (95% CI, 2.66 to 7.72, I2 = 50%)." (PMID 34372781, 2021). "Univariable Cox hazards analyses showed that subjects with male sex, Raynaud’s phenomenon onset after the age of 45, disease onset after the age of 50, cardiac involvement, PAPs > 35 mm Hg, DLCO <70%, FVC <65%, SRC, anemia, CRP > 5 mg/l, and albumin < 35 g/l had a higher risk of death." (PMID 34876194, 2021). "Malaria, fever, and CRP > 5 mg/L were major factors associated with anemia in Popokabaka." (PMID 33801005, 2021). "Low eGFR and high CRP were individually associated with the onset of anaemia." (PMID 34372781, 2021). "The 2SLS PheWAS and two-sample MR analysis found the CRP was protectively associated with disorders of fluid, electrolyte, and acid-base balance, cerebral ischemia, electrolyte imbalance, anemia of chronic disease, encephalitis, psychophysical visual disturbances, and aseptic necrosis of bone." (PMID 34386016, 2021). "Logistic regression analysis using model 3 showed that age ≥65 years, female sex, albumin level ≤3.5 g/dl, difference between sodium and chloride concentrations (Na–Cl) ≤30 mEq/L, and CRP level ≥0.3 mg/dl were also independent risk factors for increased prevalence of anemia (JSDT2 Criteria)." (PMID 32687544, 2020).
anemia (continued). "The final model was fitted on 1608 TB cases, mortality was significantly associated with age above 70 years (p = .001), alcohol abuse (p < .001), CCI ≥2 (p = .01), weight loss (p = .02), anemia (p = .01) and C-reactive protein above 100 mg/L at time of diagnosis (p < .001)." (PMID 32497102, 2020). "CRP didn’t show significant association or prediction of anemia." (PMID 33017433, 2020). "Multiple regression analysis revealed that the progression of G category was a significant risk factor for anemia; other risk factors included female sex, low serum albumin level, narrower difference between sodium and chloride concentrations, and high serum CRP level." (PMID 32687544, 2020). "However, it is important to point out that 13% of the patients had co-excising cancer, which also can result in elevated C-reactive protein, anemia and weight loss, nevertheless the association did persist after adjusting for CCI." (PMID 32497102, 2020). "However, the two groups had comparable baseline levels of mean serum ferritin, CRP, and transferrin, mean transferrin saturation, and frequencies of anemia, iron deficiency, and iron deficiency anemia." (PMID 32724619, 2020). "Moreover, ESR and CRP concentrations at pre-ATT were independently associated with increased odds for occurrence of anemia at day 60 of therapy, despite an overall improvement of Hb values detected upon anti-TB treatment initiation." (PMID 30718725, 2019). "Since iron deficiency and inflammation (reflected by CRP) are well-known causes of anemia and these factors have positive relationships with EPO levels, we excluded patients with iron deficiency (i.e., ferritin levels ≤50 ng/dL) and elevated CRP (greater than the median value)." (PMID 31619722, 2019). "Age of diagnosis > 60 years, dcSSc subtype, telangiectasia, scleroderma renal crisis, severe dyspnea NYHA functional classes III and IV, a shorter distance at the 6MWD, FVC < 70%, DLCO < 70%, PH, valvular disease, anemia, CRP > 8 mg/l, and cancer were associated with a worse prognosis." (PMID 30944015, 2019). "Elevated ferritin level, serum transferrin, transferrin receptor (TfR), TIBC, erythrocyte sedimentation rate, and C-reactive protein concentrations, and reduced serum iron concentrations and transferrin saturation are usually associated with anemia of chronic disease." (PMID 30237895, 2018). "This implies that hepcidin, in contrast to exclusively inflammatory parameters such as CRP and leukocytes, might be a useful parameter for diagnosis of a true iron deficiency in patients with anemia and active inflammation." (PMID 30089125, 2018). "An elevated CRP concentration was associated with anemia in 8 of 14 surveys (0 of 5 surveys in low- and moderate-infection groups and 8 of 9 surveys in high- and very high–infection groups), whereas elevated AGP was associated with anemia in 10 of 11 surveys (data not shown)." (PMID 28615260, 2017). "Indeed, we found that anemia, higher CRP level, and higher AHI were significantly associated with a higher Rutherford grade." (PMID 27760183, 2016). "Elevated baseline CRP (aOR 3.25, 95% CI: 1.55–6.81) and IP-10 (aOR 1.89, 95% CI: 1.05–3.39), detectable plasma LPS (aOR 2.39, 95% CI: 1.13–5.06), and the established TB risk factors anemia and hypoalbuminemia were independently associated with incident TB." (PMID 25719208, 2015). "Disease moderate activity as well as increased CRP was strongly associated with comorbid anemia." (PMID 25705682, 2015). "Here this therapeutic attitude could be proposed with a score ≥+10, which corresponds to a CRP level greater than 5 mg/L associated to any one criteria among: male gender, age>15 years, tachycardia, anemia, or thrombocytopenia." (PMID 24069477, 2013). "Estimated anemia prevalence was 34.4% (95% CI: 32.0, 36.7), iron depletion 47.5% (95% CI: 45.1, 49.9) and folate deficiency 28.8% (95% CI: 26.8, 30.8); the effect of inflammation was minimal (4% with CRP >5 mg/L)." (PMID 24260293, 2013).
anemia (continued). "Low-grade fever, abdominal pain; anaemia; increased serum creatinine and CRP, malaise, weight loss." (PMID 21957932, 2011). "Abdominal pain, weight loss, anaemia, and elevated CRP were present in all of them." (PMID 20811612, 2010). "These variations in results could be attributed to socioeconomic status, the use of IFA supplementation, the prevalence of other anemia-causing factors, and different cut-off points of serum ferritin to define anemia, along with the use of CRP to adjust the impact of ferritin limitation." (PMID 39928589, 2025). "The patient demonstrated hematological abnormalities (severe anemia and thrombocytopenia), evidence of dyslipidemia, micronutrient deficiencies (vitamin D and iron), mildly impaired renal function, and a markedly elevated CRP indicating significant systemic inflammation." (PMID 41170218, 2025). "For instance, a study to determine if stunting could have an effect on the severity of malaria-associated anaemia in African children reported that children who were stunted were at an increased risk of severe anaemia and high serum concentrations of C-reactive protein and sTfR." (PMID 38474829, 2024). "The association between anemia and inflammation seems to be relatively weak, because despite the significant correlations between CRP and hemoglobin levels in anemic patients the prognostic impact of anemia seems to be significant even after correcting for CRP." (PMID 35160156, 2022). "Despite the known association of IL-6 with anemia and CRP levels in RA, only a limited number of small or post hoc studies have evaluated the impact of biologic or targeted synthetic disease-modifying anti-rheumatic drugs (bDMARDs or tsDMARDs) on Hb and CRP levels." (PMID 36544236, 2022). "In addition, lymphopenia, elevated levels of the immune biomarkers C-reactive protein (CRP), interleukin 6 (IL-6), neopterin or ferritin, low levels of the iron transfer protein transferrin or testosterone deficiency and anemia were shown to be associated with an adverse outcome." (PMID 34677368, 2021). "However, when considering predictors for diagnosing an underlying cause of anaemia, the statistically most efficient subset contains, besides a patient’s age, nine tests (i.e. CRP, ESR, ferritin, folic acid, haemoglobin, leukocytes, eGFR, reticulocytes and serum iron)." (PMID 32736551, 2020). "Factors associated with anemia in bivariate logistic regression models were younger age, HbAS, HbSS, homozygous α+thalassemia, malaria, vitamin A deficiency, iron deficiency, greater plasma CRP and AGP concentrations and lower plasma folate and lower vitamin B-12 concentrations." (PMID 28671630, 2017). "Interestingly, LT was accompanied byseveral markers of increased HF severity, including higher BNP and CRP levels, moresevere renal dysfunction, and anemia, yet testosterone deficiency remained anindependent predictor of readmission within 90 days of hospital discharge." (PMID 26200897, 2015). "Including CRP and hepcidin in the diagnostic algorithm for anemia may better discriminate between classic iron-deficiency anemia (low hepcidin levels) and iron-deficiency anemia in the context of anaemia of inflammation or chronic disease (elevated hepcidin levels)." (PMID 23091709, 2012). "Patients with metabolic acidosis had a less favorable graft profile, with lower eGFR, higher creatinine, and higher proteinuria, along with lower hemoglobin, more frequent anemia, and higher CRP." (PMID 41598252, 2026). "Laboratory evaluation revealed severe anemia with reticulocytosis, mixed hyperbilirubinemia, elevated lactate dehydrogenase, normal cholestatic enzymes, and marked C-reactive protein elevation." (PMID 41798428, 2026). "Laboratory tests showed elevated inflammatory markers (C-reactive protein 248 mg/L, erythrocyte sedimentation rate 102 mm/h), mild anemia and wound swab culture/sensitivity positive for Pseudomonas aeruginosa, sensitive to meropenem and amikacin." (PMID 42087254, 2026).